APOB (apolipoprotein B)
Diseases named in the same sentence as APOB in open-access papers (continued):
Sharing a sentence is not in itself a finding about the gene and the disease.
atherosclerosis (continued). "Previous studies have also reported that acute ischemic stroke is associated with increased apoB/AI ratio in plasma and a high ratio of apoB/AI can also accelerate the increase in artery intima-media thickness and the risk of atherosclerosis." (PMID 31479420, 2019). "Sub-endothelial retention of APOB-containing lipoproteins is an initiating event in atherogenesis, and high plasma levels of APOB is considered a risk factor for atherosclerosis, whereas low levels are supposed to provide protection." (PMID 31098302, 2019). "The main cause of the development of atherosclerosis is a disruption of lipid metabolism associated with dysfunction of apolipoprotein B (apoB)." (PMID 31212708, 2019). "Because of this, the strong association between plasma apoB-100 lipoproteins and the clinical manifestations of atherosclerosis is to be expected." (PMID 29966388, 2018). "Atherosclerosis is caused by the subendothelial retention, or trapping, of cholesterol-rich, apolipoprotein B (apoB)-containing lipoproteins, particularly low-density lipoprotein (LDL) and remnants." (PMID 29462670, 2018). "xi) Apolipoprotein B (Apo B) R3500Q, that is considered one of the most common single site mutations in the human ApoB gene; results in mild to severe hypercholesterolaemia and an increased risk for early onset atherosclerosis." (PMID 28086795, 2017). "We investigated the relationships of HDL’s size and protein cargo with its cholesterol efflux capacity using APOB-depleted serum and HDLs isolated from five inbred mouse strains with different susceptibilities to atherosclerosis." (PMID 26673204, 2016). "Of course, a deeper risk analysis would be needed, not only with respect to atherosclerosis, but also as altered ApoB levels have been associated with neuropathology and infection susceptibility." (PMID 26519425, 2016). "Diabetes and atherosclerosis are associated with disorders of lipids and lipoproteins, notably high apolipoprotein B (apoB) and low apolipoprotein A1 (apoA1) are well established." (PMID 25318463, 2014). "ApoB and ApoA-I are the two major apolipoproteins involved in lipid transport and in the processes causing atherosclerosis and its complications." (PMID 24949011, 2014). "Absence or very low values of ery-apoB are associated with clinical and subclinical atherosclerosis." (PMID 24069429, 2013). "In conclusion, absence or very low ery-apoB is associated with the presence of clinical and subclinical atherosclerosis." (PMID 24069429, 2013). "In the Cardiovascular Risk in Young Finns Study, apoB and apoA-I measured in children and adolescents reflected a lipoprotein profile predisposing to the development of subclinical atherosclerosis in adulthood." (PMID 23359805, 2013). "Our study confirmed the association of ery-apoB with clinical and subclinical atherosclerosis in an extended study population." (PMID 24069429, 2013). "In type I DM mild changes in shape and content of atherogenic apoB occur that predispose patients to increased risk of atherosclerosis." (PMID 22811893, 2012). "Of the various classes, apoB-lipoproteins have been of great interest owing to their enormous capacity to transport large amounts of triglycerides and their association with atherosclerosis and coronary artery disease." (PMID 22353470, 2012). "The association of diabetes and atherosclerosis with disorders of lipids and lipoproteins, notably high apolipoprotein B (apoB) and low apolipoprotein A1(apoA1) is well established." (PMID 22811893, 2012). "Elevated levels of apoB have been correlated with an increased risk of atherosclerosis and coronary heart disease." (PMID 20158877, 2010). "The association between the ApoB:ApoA-I ratio and development of atherosclerosis and cardiovascular disease has been shown." (PMID 20028534, 2009). "Because high concentration of apoB has been implicated as risk factor for the development of atherosclerosis, reduction of apoB suggests the beneficial effect of taurine." (PMID 18925970, 2008).
atherosclerosis (continued). "Higher concentrations of serum lipids and apolipoprotein B100 (apoB) are major individual risk factors of atherosclerosis and coronary heart disease." (PMID 18925970, 2008). "The most probable explanation for the findings is that ApoB causes atherosclerosis by triglyceride-rich lipoproteins, namely, celiac microparticles (CM), very low-density lipoproteins (VLDL) and their respective residues, cholesterol-rich low-density lipoproteins (LDL), and lipoprotein (a)." (PMID 41030852, 2025). "In addition, athletes who are amenorrheic have higher levels of cholesterol, apolipoprotein B, and low-density lipoprotein, which are risk factors for development of atherosclerosis." (PMID 40918887, 2025). "Notably, the locus tagged by rs13414987 (APOB) was jointly associated with HF and MI (P = 1.35 × 10−8), implicating a gene central to lipid metabolism and atherosclerosis." (PMID 40630117, 2025). "Additionally, the densities of CD20+ B- and CD4+ T-lymphocytes were associated with atherosclerosis- and inflammation-related changes, such as the accumulation of apolipoprotein B-100 and serum amyloid A, and densities of CD68+ and CD163+ macrophages." (PMID 40498464, 2025). "Moreover, high ApoB/ApoA1 levels were associated with subclinical atherosclerosis and unstable plaque disease." (PMID 38310324, 2024). "It was the balance between ApoB-specific conventional and regulatory T lymphocytes reaching arterial wall that determined susceptibility of apolipoprotein E deficient (ApoE−/−) mice to atherosclerosis." (PMID 39061983, 2024). "Importantly, the Cardiovascular Risk in Young Finns Study showed that an increased ApoB : A1 in healthy young individuals reflected a predisposition to subclinical atherosclerosis in adulthood." (PMID 38048621, 2024). "Moreover, we will elaborate upon the molecular mechanisms regarding the pathophysiology of atherosclerosis, and we will discuss the disorders associated with the APOB gene mutations, and the potential role of various drugs as therapeutic targets." (PMID 38393015, 2024). "Future studies, beyond the scope of this work, will likely reveal more in-depth information about the dynamic correlation between CVD-related clinical parameters and enrichment of APOB+ motifs in atherosclerosis-related pathogenic CD4+T cells such as exTregs and effector/memory subsets." (PMID 38571941, 2024). "Apolipoprotein-B (APOB)-containing lipoproteins cause atherosclerosis." (PMID 39196121, 2024). "These patients with HoFH all had high plasma levels of LDL-C because the LDLRs were unable to function normally in the removal of LDL particles, and biochemically, apoB could have caused atherosclerosis." (PMID 39660112, 2024). "There was an independent association between higher concentrations of serum amyloid A and Z-score, body mass index, apolipoprotein B, and carotid intima-media thickness, indicating the importance of this inflammatory biomarker in identifying the early risk of atherosclerosis." (PMID 37341220, 2023). "An independent association between higher concentrations of serum amyloid A and Z-score, body mass index, apolipoprotein B, and carotid intima-media thickness was observed, indicating the importance of this inflammatory biomarker in identifying the early risk of atherosclerosis." (PMID 37341220, 2023). "Specifically, in the case of atherosclerosis some evidence suggests homocysteine thiolactone, which, like glucose and lipid peroxides, can bind to apoB, may be associated with ASCVD incidence." (PMID 36873390, 2023). "APOB is encoded by the APOB, a gene with 29 exons and 28 introns in its structure, located in chromosome 2, and many SNVs in this gene have been associated with disorders in lipid metabolism, a main risk factor observed in patients with atherosclerosis." (PMID 35440891, 2022).
atherosclerosis (continued). "Studies also demonstrate that the absolute risk for atherosclerosis in many people with high apoB is low, albeit the relative risk might be twice that of subjects with low apoB." (PMID 36439997, 2022). "ApoB is associated with the development of dyslipidemia and atherosclerosis, which could be used in diagnosis and therapy of the atherogenic dyslipoproteinemias." (PMID 35625131, 2022). "Aside from its role as a biomarker for diagnosis and prognosis of ASCVD risk, apoB may also have therapeutic potential for treatment of atherosclerosis." (PMID 35371605, 2022). "Moreover, the ApoB/ApoA1 ratio was associated with femoral artery atherosclerosis as measured both as intima-media thickness and plaque occurrence; and carotid artery atherosclerosis measured by intima-media thickness." (PMID 34996506, 2022). "Autoantibodies against native p210, the 3136–3155 amino acid sequence of the LDL protein apolipoprotein B-100 (apoB100) are common in humans and have been associated with less severe atherosclerosis and decreased risk for cardiovascular events in clinical studies." (PMID 33907226, 2021). "Whereas, therapeutic interventions that aim to stabilize and/or expand ApoB+ Tregs hold promise for atherosclerosis prevention and treatment, immunomodulatory therapies causing destabilization of Tregs naturally aggravate progression of atherosclerotic lesions." (PMID 35097027, 2021). "In addition to the involvement of ApoB in atherosclerosis and CVD, ApoB-related dyslipidemia is linked to another global epidemic, nonalcoholic fatty liver disease (NAFLD), which affects around 20%–30% of the adult population in Western countries." (PMID 34236046, 2021). "In addition, MCP-1 deletion reduced atherosclerosis progression in transgenic mice overexpressing human ApoB and in low-density-receptor-deficient mice." (PMID 33803115, 2021). "Specific LysMCre-driven deletion of Tet2 in Tregs led to deranged suppressor function, phenotypic dysregulation and eventually to a phenotypic switch toward a proinflammatory TH17/TFH effector phenotype, similar to what has been described for pathogenic ApoB-reactive autoimmunity in atherosclerosis." (PMID 35087883, 2021). "Lp(a) does increase the risk of atherosclerosis beyond that captured by apoB but this may only matter in those whose LDL-C or apoB are also elevated." (PMID 33598387, 2021). "This indicates that age-related thymic involution might predispose elderly individuals to atherosclerosis by biasing the balance of ApoB-specific Teff versus Treg cells." (PMID 31988649, 2020). "The ApoB/ApoA1 ratio is linked to early atherosclerosis as well." (PMID 32717783, 2020). "It is speculated that the significance may be a genetic marker that is in linkage with the functional mutation of the ApoB gene itself, leading directly to the formation of atherosclerosis, or by affecting cholesterol." (PMID 32493216, 2020). "However, the Apolipoprotein B (apoB) concentration reflects the number of atherogenic particles and is closely associated with atherosclerosis." (PMID 29805388, 2018). "Lp(a), which can pass through the endothelial barrier and preferentially retain in the arterial intima by binding to the extracellular matrix via both apoB and apo(a), is the primary carrier of oxidized phospholipids associated with vascular inflammation and atherosclerosis." (PMID 30181995, 2018). "In addition, several other studies have demonstrated that polymorphisms of the apoB gene are associated with atherosclerosis." (PMID 29514644, 2018). "ApoB gene polymorphisms have been suggested to be associated with atherosclerosis." (PMID 29514644, 2018).
atherosclerosis (continued). "Accordingly, analysis of specialized lipid parameters showed statistically significant increase in the ApoB/ ApoA1 ratio which associated with the development of clinical cardiovascular disease and with early atherosclerosis onset; moreover is considered the stronger predictor of vascular events." (PMID 28806974, 2017). "Atherosclerosis, the underlying pathology of most cardiovascular diseases, is triggered by the retention of apolipoprotein B (apoB)-containing lipoproteins in the arterial wall through electrostatic interactions with glycosaminoglycan (GAG) side chains of proteoglycans." (PMID 28316603, 2017). "High plasma ApoB levels are a factor contributing to plaques that cause atherosclerosis." (PMID 25889118, 2015). "One candidate gene within the Chromosome 6 peak region associated with atherosclerosis is Apobec1, the apolipoprotein B (ApoB) mRNA-editing enzyme, which plays a role in the regulation of ApoB, a critical component of low-density lipoprotein, by editing ApoB mRNA." (PMID 25344410, 2014). "We next hypothesized that the association at this locus may be mechanistically related to the role of Apobec1 in editing its primary target, ApoB, as elevated plasma ApoB is a known risk factor for atherosclerosis." (PMID 25344410, 2014). "A high APOB serum level may be associated with hyperlipidemia and atherosclerosis, and therefore, the TT genotype in rs281437 may be a risk factor for atherosclerosis cases." (PMID 25310099, 2014). "The two peptides were selected for coupling based on our hypothesis that they share high homology with ApoB protein which is associated with atherosclerosis." (PMID 24349031, 2013). "Low ratio of ApoA1 to ApoB reflects the potential risk of atherosclerosis." (PMID 24160749, 2013). "Furthermore, knocking out apoA-I resulted in an accelerated atherosclerosis development in several animal models (i.e. the human apoB-transgenic female mice; the LDL receptor-deficient; the LDL receptor/apoE-deficient mice)." (PMID 23552612, 2013). "Then, healthy children with diabetic parent(s) are at greater risk of atherosclerosis and screening for plasma apoA and apoB levels may be helpful in these children." (PMID 22811893, 2012). "Elevated apoB is a hallmark of several inherited disorders associated with atherosclerosis." (PMID 22496881, 2012). "On the other hand, in Chinese type 2 diabetic patients with concomitant coronary heart disease, the PPARγC161 ༠ T genotype was associated with reduced severity of atherosclerosis, in part medicated by improved lipid metabolism of decreased the triglycerides and apoB levels." (PMID 21092182, 2010). "Based on this knowledge attempts have been made to develop immunomodulatory therapy for prevention of cardiovascular disease and pilot vaccines containing apolipoprotein B (apo B) antigens have been shown to significantly reduce atherosclerosis in apolipoprotein E deficient (Apoe-/-) mice." (PMID 21126329, 2010). "Results suggest that ApoB may be the best target for treatment in people at risk for atherosclerosis and cerebrovascular disease." (PMID 20028534, 2009). "In fact, the ratio ApoB:ApoA-I may be the best predictor of risk of atherosclerosis and likewise the optimal measure to assess new lipid-lowering medication, as treatment regimens that lower ApoB are likely to be most effective in reducing plaque formation." (PMID 20028534, 2009). "Finally, APOB was associated with both innate and adaptive immunity, playing a role in host defense and modulating T cells in chronic inflammatory conditions such as atherosclerosis." (PMID 41241706, 2025). "ApoB blood concentrations have strong associations with subclinical atherosclerosis and incident ASCVD." (PMID 36272600, 2022).
atherosclerosis (continued). "Lipoproteins were also associated with incident CVD with apolipoprotein B and free cholesterol in very low-density lipoproteins showing the strongest associations and overall lower density lipoproteins showing stronger direct associations with atherosclerosis and CVD events." (PMID 31102408, 2019). "In addition, high apoB/apoA-I ratio has been associated with early atherosclerosis." (PMID 30842338, 2019). "Currently, it has been well established that atherosclerosis is both a component associated with metabolic disorder and a chronic inflammatory process in the arterial wall, which is induced initially by the subendothelial deposition of apolipoprotein B-containing lipoproteins (apoB-LPs)." (PMID 31886303, 2019). "Hepatic deletion of SEC16B in mice markedly reduces circulating APOB, triglycerides and cholesterol, while conferring robust protection against atherosclerosis and cardiac dysfunction and maintaining liver health." (PMID 42032080, 2026). "Despite the beneficial hepatic effect of FGF1, ApoB lipoprotein particles (especially LDL-cholesterol) are central to atherosclerosis development and even with effective LDL-cholesterol control, residual risk is prevalent in patients with metabolic syndrome." (PMID 41541501, 2026). "Human ApolipoproteinB (ApoB) exists in two isoforms that are packaged into low density lipoprotein particles and are major contributors to atherosclerosis." (PMID 41099152, 2026). "This review integrates recent structural and biochemical insights into apolipoprotein B (apoB) containing lipoproteins to highlight how factors beyond cholesterol levels contribute to atherosclerosis." (PMID 40549487, 2025). "The glycation process of LDL particles on ApoB can increase the extent of atherosclerosis, particularly in diabetic patients." (PMID 40597178, 2025). "It is a receptor for apolipoprotein B (ApoB), which plays a crucial role in the development of atherosclerosis." (PMID 40868056, 2025). "A transcriptomic study of human APOB-specific CD4 T cells suggests that the transformation of Tregs into exTregs promotes the development of atherosclerosis in both mice and humans." (PMID 39944697, 2025). "Vaccine-based immunotherapy against atherosclerosis-relevant antigens, such as ApoB-derived peptides, has shown promise in preclinical models by expanding FoxP3+ regulatory T cells and IL-10-producing B cells." (PMID 40833492, 2025). "Recent studies have suggested that excessive ApoB lipoproteins can be taken up by KCs in the liver, triggering the secretion of factors that modulate atherosclerosis." (PMID 41252283, 2025). "Nevertheless, CVD events in some APOB mutation carrier emphasise that moderate, lifelong LDL elevation can still promote atherosclerosis if untreated." (PMID 41398288, 2025). "Apolipoprotein B (Apo‐B) is part of the structure of LDL, and its mutation causes LDL to remain in the blood more than usual, and as a result, the possibility of atherosclerosis increases." (PMID 40123054, 2025). "Lipid antigens in plaque, including apolipoprotein B (ApoB) and cholesterol crystals, enhance innate immunity, promoting inflammatory and chemokine production and driving atherosclerosis progression." (PMID 40927754, 2025). "Higher levels of APOB signify more LDL particles, which more accurately predict atherosclerosis risk than LDL alone." (PMID 40892857, 2025). "Each SD increase in apoB corresponded to an OR of 2.386 for significant coronary stenosis and an OR of 2.433 for left main atherosclerosis." (PMID 41374382, 2025). "While atherosclerosis begins with the subendothelial retention of apolipoprotein B (ApoB)-containing lipoproteins​, its progression is increasingly recognized as a consequence of complex cellular and extracellular dynamics within the plaque microenvironment." (PMID 40172727, 2025).